SPOCK1 (SPARC (osteonectin), cwcv and kazal like domains proteoglycan 1)
Description:
May play a role in cell-cell and cell-matrix interactions. May contribute to various neuronal mechanisms in the central nervous system.
Synonyms: SPOCK; TIC1; testican-1; TESTICAN
Tractability: Antibody: UniProt places it where antibodies can reach, with medium confidence; UniProt predicts a signal peptide or a membrane-spanning region; its Gene Ontology location is reachable by antibodies, with medium confidence. PROTAC: ubiquitination databases record sites on it; its protein half-life has been measured.
Gene: Protein-coding gene on chromosome 5 (136,975,298 to 137,598,379, reverse strand). Ensembl gene ENSG00000152377.
Subcellular location: Secreted, extracellular space, extracellular matrix
Subcellular location (Human Protein Atlas): Vesicles; Predicted to be secreted
Gene Ontology:
Molecular function: calcium ion binding; cysteine-type endopeptidase inhibitor activity; extracellular matrix structural constituent; metalloendopeptidase inhibitor activity; protein binding; serine-type endopeptidase inhibitor activity
Biological process: negative regulation of cell-substrate adhesion; negative regulation of neuron projection development; cell adhesion; central nervous system neuron differentiation; nervous system development; neurogenesis; neuron migration; regulation of cell growth; regulation of cell-substrate adhesion
Cellular component: extracellular matrix; extracellular region; cytoplasm; gel phase of interstitial matrix; neuromuscular junction; node of Ranvier; postsynaptic density; sarcoplasm
Genetic constraint (gnomAD): Loss-of-function variants: 20 observed, 49.6 expected, observed/expected ratio (o/e) 0.4, 90% interval 0.28 to 0.59. The upper end of that interval is the gene's LOEUF score, 0.59, which puts it in group 2 of 6, group 1 being the genes least tolerant of losing a copy. Missense variants: 480 observed, 538.59 expected, observed/expected ratio (o/e) 0.89, 90% interval 0.83 to 0.96. Synonymous variants: 218 observed, 219.24 expected, observed/expected ratio (o/e) 0.99, 90% interval 0.89 to 1.11.
Homologues: Orthologues: chimpanzee SPOCK1 (99% identical), pig SPOCK1 (97% identical), rat Spock1 (95% identical), mouse Spock1 (95% identical), macaque SPOCK1 (89% identical), rabbit SPOCK1 (84% identical), dog SPOCK1 (83% identical), guinea pig SPOCK1 (81% identical), zebrafish spock1 (64% identical), Drosophila melanogaster Cow (28% identical), Caenorhabditis elegans test-1 (16% identical). Paralogues in human: SPOCK3 (52% identical), SPOCK2 (45% identical), KIAA1210 (8% identical).
Diseases named in the same sentence as SPOCK1 in open-access papers:
SPOCK1 is named in the same sentence as 89 diseases in open-access papers, as found by Europe PMC text mining. Sharing a sentence is not in itself a finding about the gene and the disease. The quoted sentences say what the papers report.
hepatocellular carcinoma (23 papers, 2015 to 2025). A malignant tumor that arises from hepatocytes. "When fibroblasts are stimulated by cancer cells like hepatoma, they release EVs with tumor-promoting cargo (e.g., SPOCK1/testican-1), which tend to home back to tumor sites and support cancer progression." (PMID 40530018, 2025). "For instance, fibroblasts stimulated by hepatoma cells exhibit a significant upregulation of SPOCK1/testican-1 pathways, promoting the progression of hepatoma cells." (PMID 40078996, 2025). "For instance, fibroblasts activated by hepatoma cells demonstrate a notable elevation of SPOCK1/testican-1 pathways, facilitating the advancement of hepatoma cells." (PMID 40530018, 2025). "Expression levels of miR-139-5p, miR-193a-5p, and miR-940 are reduced in hepatocellular carcinoma, whereas expression of their shared target gene, the oncogene SPOCK1, is increased." (PMID 41465470, 2025). "The most prominent change was a more than tenfold upregulation of SPOCK1/testican-1 in the EVs of both hepatoma cell lines." (PMID 37762298, 2023). "miR-139-5p, miR-940, and miR-193a-5p also inhibit the growth of hepatocellular carcinoma by targeting SPOCK1." (PMID 36833394, 2023). "Circ_0061395 can promote the development of hepatocellular carcinoma by regulating the miR-1182/SPOCK1 signalling axis." (PMID 37428781, 2023). "Because in human and experimental hepatocellular carcinoma its stromal expression was hardly detected after secretion, SPOCK1 is likely to be cleared by the circulation." (PMID 35186754, 2022). "To this end, we performed a series of assays on an experimental hepatocarcinogenesis model, studied human liver cancers, and quantified how SPOCK1 silencing or upregulation influenced the aggressiveness of hepatoma cell lines." (PMID 35186754, 2022). "SPOCK1 expression was assessed on human liver cirrhosis and hepatocellular carcinoma of various etiologies." (PMID 35186754, 2022). "SPOCK1 downregulation of hepatoma cell lines by siRNA inhibited cell proliferation, upregulated p21 and p27, and interfered with pAkt and CDK4 expression." (PMID 35186754, 2022). "TTN-AS1 promotes proliferation, migration, invasion, and epithelial-mesenchymal transformation (EMT) of hepatocellular carcinoma cells by regulating the miR-139-5p/ sparc/osteonectin, cwcv, and kazal-like domains proteoglycan 1 (SPOCK1) axis." (PMID 34903127, 2021). "More interestingly, a number of studies have demonstrated that SPOCK1 plays a critical role in prostate cancer recurrence, glioblastoma invasion, and hepatocellular carcinoma progression." (PMID 25623055, 2015). "In hepatocellular carcinoma, TTN‐AS1 could interact with miR‐139‐5p to modulate SPOCK1 expression, which then contributed to hepatocellular carcinoma cell multiplication, invasion, and EMT." (PMID 37528740, 2023). "Among the proteins with increased EV abundance, we identified SPOCK1/testican-1, a proteoglycan increasingly accepted as oncogenic that displayed over 10-fold elevation in the treatment-modulated EVs of both hepatoma cell lines." (PMID 37762298, 2023). "LX2-derived EVs induced over tenfold upregulation of SPOCK1/testican-1 in hepatoma EV cargo." (PMID 37762298, 2023). "SPOCK1 mRNA decreased in SPOCK1-silenced and increased in SPOCK1-transfected hepatoma cell lines." (PMID 35186754, 2022). "In hepatoma cell lines, the cytoplasmic SPOCK1 colocalized with mitochondrial markers, such as MitoTracker and TOMM20, a characteristic protein of the outer membrane of the mitochondrion and could be detected in the cell nucleus." (PMID 35186754, 2022). "Apparently, although the expression of SPOCK1 is very low in healthy hepatocytes, their injuries facilitate the upregulation of the proteoglycan, and its expression increases in liver cirrhosis and hepatocellular carcinoma." (PMID 35186754, 2022).
hepatocellular carcinoma (continued). "Immunohistochemical analysis of 76 surgically removed liver specimens revealed that the expression of SPOCK1 is a characteristic feature of human liver cirrhosis and cancer, and its accumulation occurs in the cytoplasm of hepatocytes and the cells of hepatocellular carcinoma." (PMID 35186754, 2022). "It was reported that hsa-miR-940 could inhibit the growth of hepatocellular carcinoma by targeting SPOCK1." (PMID 34079579, 2021). "miR-139-5p can also inhibit the growth of hepatocellular carcinoma by targeting SPOCK1." (PMID 33954179, 2021). "Recently, SPOCK1 was also found to be overexpressed in hepatocellular carcinomas." (PMID 25623055, 2015). "SPOCK1 has been demonstrated to function in cell proliferation, migration, and apoptosis in certain types of cancer, such as pancreatic ductal adenocarcinoma, lung cancer, colorectal cancer, and hepatocellular carcinoma, indicating that SPOCK1 plays an important role in oncogenesis." (PMID 36611136, 2023). "Although SPOCK1 is an extracellular matrix proteoglycan, its concentration increases in the cytoplasm of hepatocytes starting with very low expression in the normal cells and then appearing in much higher quantities in cells of cirrhotic human liver and hepatocellular carcinoma." (PMID 35186754, 2022). "Previous publications have demonstrated a role for SPOCK1 in cancer types such as breast cancer, prostate cancer, glioblastomas, urothelial carcinomas, ovarian cancer, esophageal squamous cell carcinomas, gallbladder cancer, lung cancer, and hepatocellular carcinomas." (PMID 28486750, 2017). "In addition, our finding is consistent with previous studies demonstrating that SPOCK1 plays a critical role in multiple cancers, including prostate cancer, glioblastoma, hepatocellular carcinoma, esophageal squamous cell carcinoma, lung carcinoma, and gall bladder carcinoma." (PMID 27626636, 2016). "A tyrosine kinase array revealed that inhibition of SPOCK1 in the liver cancer cells altered MAPK signaling and downregulated several members of the Sarc family, all related to the aggressivity of the hepatoma cell lines." (PMID 35186754, 2022). "Thus, our results on the human hepatocellular cancer (HCC) and mouse hepatocarcinogenesis models, together with literature data, provided confirmation for the presence of SPOCK1 in diseased hepatocytes of cirrhotic liver and cancer cells." (PMID 35186754, 2022). "The granular cytoplasmic SPOCK1 reaction raised the possibility that the proteoglycan localizes in the mitochondria; thus, double fluorescent immunostainings were carried out with SPOCK1 antibody together either with TOMM20 or mitochondrial marker (MitoTracker-red, M22425) on hepatoma cell lines." (PMID 35186754, 2022). "Although mRNA expression of SPOCK1 depends upon the experimental conditions when using hepatoma cell lines, the intracellular presence of the protein is not influenced either by silencing or transfection." (PMID 35186754, 2022). "Our studies on human liver specimens support the notion that SPOCK1 is upregulated in cirrhotic liver and hepatocellular carcinoma, but the localization is not stromal." (PMID 35186754, 2022). "In a previous study, MMP-9 was up-regulated by SPOCK1 in a hepatocellular carcinoma cell line and treatment with an MMP-9 inhibitor significantly inhibited the invasion ability of SPOCK137, suggesting SPOCK1 may induce ECM remodeling through MMPs." (PMID 32555336, 2020).
lung carcinoma (19 papers, 2015 to 2024). "Additionally, in vivo studies of lung cancer demonstrated that SPOCK1 is not only associated with metastasis but also induces the EMT, suggesting the extensive roles of SPOCK1 in promoting cancer cell invasiveness and metastasis through involvement in the EMT process." (PMID 31182131, 2019). "SPOCK1 is involved in facilitating EMT in lung cancer, and its high expression has been correlated with malignant invasive characteristics, the formation of an immunosuppressive TME, and poor prognosis." (PMID 39595089, 2024). "In lung cancer, SPOCK1 expression was elevated in osimertinib-resistant tumor cells, and its knockdown inhibited the proliferation of osimertinib-resistant cells and overcame resistance." (PMID 37046698, 2023). "In order to explore the potential clinical value of SPOCK1, we conducted further analysis on its relationship with several commonly used chemotherapy drugs for lung cancer." (PMID 38087364, 2023). "SPOCK1 can also be the regulator of brain metastasis of lung cancers, raising the opportunity to use the protein as a predictive tumor marker." (PMID 35186754, 2022). "Two of the top upregulated genes—AXL and SPOCK1 for H1975 and H23, respectively—were of interest as they are known to be involved in signaling pathways important to lung cancer development and resistance to targeted therapy." (PMID 33712563, 2021). "SPOCK1 was highly expressed in various cancers, including prostate cancer, pancreatic cancer, lung cancer and breast cancer." (PMID 33293473, 2020). "Miao identified SPOCK1 as a novel transforming growth factor-b1 (TGF-b) target gene that regulates the lung cancer cell epithelial-to-mesenchymal transition (EMT), which plays a key role in the early process of metastasis of cancer cells." (PMID 26373443, 2015). "In lung cancer, high expression of SPOCK1 correlated with poor prognosis." (PMID 36186418, 2022). "SPOCK1 is a novel TGF-β-targeted gene that regulates lung cancer epithelial cells." (PMID 36186418, 2022). "In addition, SPOCK1 is a novel TGF-β target gene that regulates the EMT of lung cancer cells." (PMID 37511221, 2023). "Moreover, the upregulation of SPOCK1 was observed in lung cancer cell A549 treated with TGF-β." (PMID 27626636, 2016). "Research has identified SPOCK1 as an independent prognostic factor in NSCLC, with the potential to become a target gene for therapy in osimertinib-resistant lung cancers." (PMID 37046698, 2023). "It is interesting to note that SPOCK1 facilitated the migration and invasion of cancer cells via the mechanism of EMT in certain types of cancers, such as gallbladder cancer 13 and lung cancer." (PMID 28940639, 2018). "As for SPOCK1, studies have proved SPOCK1 as an EMT-related marker that was closely correlated with tumorigenesis and invasiveness in gastric cancer, prostate cancer, pancreatic cancer, gallbladder cancer, and lung cancer." (PMID 34692770, 2021). "SPOCK1 is a target of TGF-β and induces epithelial-to-mesenchymal transition (EMT) in lung cancer." (PMID 31615030, 2019).
prostate carcinoma (17 papers, 2010 to 2024). A carcinoma that arises from epithelial cells of the prostate gland. "In prostate cancer, high SPOCK1 expression was related to advanced stage, T value and Gleason grade." (PMID 37046698, 2023). "In general, several tumors of epithelial origin express SPOCK1 in the cytoplasm, including prostate cancer, breast cancer, gastric cancer, and several others." (PMID 35186754, 2022). "Overexpression of SPOCK1 was observed in both naïve PCa and castration-resistant prostate cancer tissues." (PMID 31284511, 2019). "SPOCK1 is a proteoglycan protein and was reported to play vital roles in cell proliferation and motility in various cancer types, such as pancreatic cancer, gliomas, prostate cancer, gastric cancer, and so on." (PMID 36766694, 2023). "Beyond all that, though, as previously reported, SPOCK1 could promote cell proliferation in colorectal cancer 15 and prostatic cancer." (PMID 28940639, 2018). "Notably, clinical and pathological studies have demonstrated that SPOCK1 is frequently overexpressed in highly metastatic human prostate cancer tissues, thus it could be an attractive prognostic biomarker and therapeutic target in cancer treatment." (PMID 38791608, 2024). "Whether or not pBRD4 is increased as a result of SPOP mutation, and if SPOCK1 induction mediates the increased PI3K/AKT signaling in prostate cancer is unknown." (PMID 33712563, 2021). "SPOCK1 was reported to be a regulator of the ECM and is crucial for maintaining the process of tumor ECM dynamic homeostasis through regulating the activities and expressions of MMPs such as MMP-2, MMP-3, and MMP-9 in glioma, liver cancer, and prostate cancer." (PMID 36766694, 2023). "SPOCK1 is closely related to cell proliferation, adhesion, and metastasis, and it is highly expressed in a variety of cancers, including ESCC, liver, gallbladder, colon, and prostate cancer." (PMID 37753805, 2023). "Anti-metastatic properties of apigenin, mediated through direct targeting of SPOCK1 and an inactivation of Snail-Slug mediated EMT, were observed in PC-3, PC-3 M and DU145 prostate cancer cells in vitro and suppressed prostate cancer metastasis in vivo in PC-3 M-Luc mice." (PMID 32521759, 2020). "Regarding human prostate cancer, a very interesting study showed that Apigenin was able to suppress EMT either in vitro or in vivo in a dose and time-dependent manner by targeting SPARC/osteonectin, cwcv, and kazal-like domains proteoglycan 1 (SPOCK1)-snail/slug axis." (PMID 38791608, 2024).
gastric cancer (16 papers, 2016 to 2025). A primary or metastatic malignant neoplasm involving the stomach. "The elevated SPOCK1 expression has been associated with increased metastasis and a poor prognosis in patients with gastric cancer." (PMID 35221802, 2022). "A clinicopathological association study of the 102 patients with gastric cancer demonstrated that the expressions of SPOCK1, E‐cadherin, Slug and Vimentin significantly correlated with T stage, pTNM stage and lymph node metastasis, respectively (P < 0.05)." (PMID 28940639, 2018). "Gastric CAFs derived SPOCK1 was significantly associated with tumor differentiation and suppressing SPOCK1 expression in gastric CAFs facilitated the phenotypic alteration of gastric cancer cells towards CSC-like cells where AKT/mTOR and MEK/ERK pathways might participate." (PMID 35360859, 2022). "Here we present a study on the expression of emerging biomarkers SOX9, MCL-1 and SPOCK1 in a gastric cancer tissue microarray (TMA)." (PMID 35221802, 2022). "Here we studied the expression of emerging prognostic markers SOX9, MCL-1, and SPOCK1 (Testican-1) in a cohort of gastric cancer by immunohistochemistry and investigated how individual biomarkers and their combinations predict disease prognosis." (PMID 35221802, 2022). "The potential importance of SPOCK1 in gastric cancer was first raised in a genome-wide study that found SPOCK1 expression was upregulated 10-fold in gastric cancer." (PMID 35221802, 2022). "The study discovered different expression patterns of SPOCK1 and frequent nuclear and cytoplasmic SPOCK1 expression in gastric cancer." (PMID 35221802, 2022). "SPOCK1 facilitates gastric cancer cell invasion and metastasis in vitro and mechanism appears to involve Slug-induced epithelial mesenchymal transition." (PMID 35221802, 2022). "Research shows that SPOCK1 can promote the invasion and metastasis of gastric cancer through Slug-induced epithelial-mesenchymal transition." (PMID 33902514, 2021). "Other methods including stably transfected against SPOCK1 into gastric cancer cells, Western blot, migration and invasion assays in vitro and metastasis assay in vivo were also performed." (PMID 28940639, 2018). "SPOCK1, Slug and Vimentin shared markedly higher expression in gastric cancer tissues, compared with those in adjacent normal gastric mucosas (P = 0.001, P = 0.017 and P = 0.001, respectively)." (PMID 28940639, 2018). "In the current study, regarding the mechanism of SPOCK1‐mediated EMT in gastric cancer invasion and metastasis, for the first time possibly we explored the roles of Snail and Slug in the SPOCK1‐mediated EMT." (PMID 28940639, 2018). "To confirm the role of SPOCK1 in the invasion and metastasis of gastric cancer cells in vivo, we performed a lung metastasis model through the injection of tail vein in nude mice." (PMID 28940639, 2018). "SPOCK1 has been demonstrated to facilitate cancer metastasis in certain types of cancers; however, the role of SPOCK1 in the invasion and metastasis of gastric cancer remains elusive." (PMID 28940639, 2018). "The elevated expression of SPOCK1 correlates with EMT‐related markers in human gastric cancer tissue, clinical metastasis and a poor prognosis in patients with gastric cancer." (PMID 28940639, 2018). "Moreover, miR-129-5p can function as a suppressor of gastric cancer development by suppressing SPOCK1, the downstream responsive component of TGF-β1 signalling pathways." (PMID 40730640, 2025). "Glioblastoma and gastric cancer are two further instances of SPOCK1 involvement in chemotherapy." (PMID 37046698, 2023). "In gastric cancers, acquired lapatinib resistance was mediated by SPOCK1-induced EMT." (PMID 37046698, 2023). "Although SPOCK1 was discovered in 1997, the first reports related to its oncogenic potential were published after 2010, describing the implication of the proteoglycan in gastric cancer." (PMID 35186754, 2022).